BMP2 (bone morphogenetic protein 2)
Diseases named in the same sentence as BMP2 in open-access papers (continued):
Sharing a sentence is not in itself a finding about the gene and the disease.
breast cancer (79 papers, 2007 to 2025). A primary or metastatic malignant neoplasm involving the breast. "In this context, one study demonstrated that the in situ expression of BMP-2 in human breast cancer is closely associated with both EMT and microcalcification formation, depending on its cellular localization." (PMID 39859358, 2025). "In xenograft models, BMP2 can promote EMT and metastasis, and BMP2 has been associated with poor disease-free survival in breast cancer patients." (PMID 37762032, 2023). "Overexpression of BMP2 has been associated with poor disease-free survival by enhancing AKT/mTOR pathway among 272 patients with breast cancer." (PMID 37333824, 2023). "Our studies, amongst others, have presented robust evidence that breast cancer with microcalcifications is associated with poor clinical outcome and BMP-2 is upregulated in tissues with microcalcifications." (PMID 34983451, 2022). "Promoter methylation of BMP2 has been associated with breast cancer progression and drug resistance." (PMID 33461604, 2021). "In conclusion, from these experimental and translational perspectives, the complexity of BMP-2 signaling will require a detailed understanding of the involvement of specific BMP-2 variants in breast cancers." (PMID 32498363, 2020). "This study aims to investigate the possible different roles of the BMP-2 variants, cytoplasmic and nuclear variant, in both epithelial to mesenchymal transition and in microcalcifications origin in human breast cancers." (PMID 32498363, 2020). "We aimed to elucidate the mechanisms underlying the influence of BMP-2 on breast cancer progression using recombinant human BMP-2 (rhBMP-2)." (PMID 28725489, 2017). "To determine the molecular mechanisms underlying the effects of BMP-2 on breast cancer cells, we used the RT2Profiler PCR Array (Qiagen, Hilden, Germany) to detect changes in the expression of 84 genes known to be associated with tumor metastasis." (PMID 28725489, 2017). "Reduced BMP2 was evident in T3 and T4 tumours of the Luminal B subtype, in comparison with T1 and T2 tumours and the reduced expression was associated with poor overall survival in Luminal B subtype breast cancers." (PMID 37333824, 2023). "Furthermore, HB‐EGF, COX‐2, and Wnt4 as well as Bmp2 have been shown to be risk factors for sex hormone‐dependent diseases, such as prostatic hyperplasia, breast cancer, and ovarian cancer." (PMID 28588064, 2017). "Next, the frequency scatter of enrichments in the alteration of BMP2 in breast cancer patients was higher than that of the unaltered ones in the TCGA and METABRIC databases." (PMID 40936753, 2025). "To further explore the function of BMP2 in breast cancer, we used the cBioPortal online tool to analyze functional genomics." (PMID 40936753, 2025). "The importance of the molecular characterization of breast cancers is underscored by the paradoxical prognostic impact of BMP-2 and vimentin across different cancer subtypes." (PMID 39859358, 2025). "Despite the pathogenesis and etiology of this uncommon entity of breast cancer remain incompletely understood, the BMP2 alterations identified in our study represents a potentially significant finding for further investigation." (PMID 40936753, 2025). "The expression of BMP-2, in particular, is associated with a better prognosis in HER2-positive breast cancers." (PMID 39859358, 2025). "Accordingly, BMP2 antagonists were reported to block the angiogenic effects of BMP2 in breast cancer and melanoma cells." (PMID 38610001, 2024). "Bone morphogenetic protein 2 (BMP2) is most significantly upregulated in breast cancer bone metastases where it activates macrophages." (PMID 38542388, 2024). "For instance, BMP2 was shown to have both pro- and anti-migratory effects in human breast cancer cell lines." (PMID 38731813, 2024). "Analysis of breast cancer patient data revealed that BMP2 and BMP6 were significantly downregulated in tumors." (PMID 38731813, 2024).
breast cancer (continued). "BMP2 inhibits the proliferation and metastasis of tumor cells in breast cancer, colon cancer, and gastric cancer." (PMID 37118847, 2023). "In breast cancer, BMP2 can regulate EMT and stemness by upregulating CD44 and MMP11 via PI3K/AKT and Smad signalling pathways." (PMID 37333824, 2023). "Additional evidence for the involvement of BMPs in bone metastasis came from another observation that BMP2/BMP7 heterodimer inhibited colonisation of breast cancer cells in bone." (PMID 37333824, 2023). "This suggested that altered immune cell activity leads to an increase in BMP-2, eventually resulting in the occurrence of calcification in breast cancer." (PMID 36694240, 2023). "The loss of MXRA8 also led to a decrease in the expression of genes associated with breast cancer, including ADAMTS1, TIE1, and BMP2." (PMID 37762032, 2023). "BMP2 has also been shown to be involved in the BoM process among many different cancers including lung carcinoma and breast cancer." (PMID 38187400, 2023). "BMP-2/5/6/7 are observed in breast cancers and are correlated with the expression of the stem cell marker CD44." (PMID 35693928, 2022). "The aim of this study is to elucidate the role of secretion of BMP-2 by TAMs in promoting microcalcifications of breast cancer through immunohistochemical staining and co-culturing of breast cancer cells with TAMs." (PMID 34983451, 2022). "Previous studies have shown that BMP2 signaling enhances bone metastasis of mice Lewis lung carcinoma and breast cancer cells using xenografted mouse model." (PMID 36175474, 2022). "Lung metastasis of breast cancer cells by BMP2 signaling pathway is also reported in the mouse model." (PMID 36175474, 2022). "Studies have shown that BMP-2 can induce breast cancer cells to acquire osteoblastic characteristics, leading to the formation of microcalcifications." (PMID 34983451, 2022). "Further experiment demonstrated the role of secretion of BMP-2 by TAMs in promoting microcalcifications of breast cancer through co-culturing of breast cancer cells with TAMs." (PMID 34983451, 2022). "Abnormal BMP2 production by SCs microenvironment together with BMP2-driven alterations of epithelial SC fate are involved in the emergence of luminal breast cancer cells." (PMID 35047500, 2021). "Our study indicates that BMP2 promotes TNBC stemness, which is concordant with another study which shows a critical function of BMP2 in promoting breast cancer EMT and stemness through Rb signaling pathway." (PMID 34277708, 2021). "For instance, in breast cancer it has been shown that deregulation of the stem cell niche by increased expression of bone morphogenetic protein 2 (BMP2) can initiated and promote malignant stem cell transformation." (PMID 32154167, 2020). "Of interest, we frequently observed both vimentin-positive breast cancer cells and vimentin-cytoplasmic BMP-2 co-positive cells in the BT-474/CTRL group." (PMID 32498363, 2020). "In order to investigate the different role of nBMP-2 and BMP-2 in breast cancer progression, the expression of these molecules has been compared to age and evaluated in benign and malignant lesions." (PMID 32498363, 2020). "BMP8B was significantly active in primary breast cancer, while BMP2, BMP4, BMP5, BMP6, BMP8B were significantly active in liver metastasis." (PMID 31557971, 2019). "In breast cancer models, BMP-2 has also been shown to induce the proto-oncogene PI3K in osteoblasts to regulate differentiation." (PMID 28733469, 2017). "This is the first study that reveals an integrated mechanism behind the effect of BMP-2 on cancer stem cell formation and breast cancer metastasis." (PMID 28725489, 2017). "To investigate the potential role of BMP-2 in breast cancer development, we treated three breast cancer cell lines (MCF-7, MDA-MB-231, and a mouse breast cancer cell line 4T1) with rhBMP-2 for 24 h." (PMID 28725489, 2017).
breast cancer (continued). "SOSTDC1, a secreted regulator of both BMP and Wnt signalling pathways, is under expressed in breast cancer and can differentially affect signalling induced by Wnt3a, BMP-2 and BMP-7." (PMID 28733469, 2017). "A kinase inactive type II TGF-β receptor (dnTbetaRII) eliminated the anti-proliferative effect of BMP-2 in breast cancer cells by preventing the phosphorylation of Smad-1." (PMID 28733469, 2017). "BMP-2 inhibits oestradiol-induced proliferation of breast cancer cells, via upregulation of cyclin kinase inhibitor p21, which in turn inhibits the oestradiol-induced cyclin D1-associated kinase activity." (PMID 28733469, 2017). "Regarding breast cancer specifically, one study has reported that BMP-2 promotes breast tumour related angiogenesis through stimulating p38 MAPK pathway and ID-1 expression." (PMID 28733469, 2017). "Smad-independent signalling through p38 and JNK pathways is involved in BMP-2 induction of Tenascin-W and overexpression of Tenascin-W in the stroma of breast cancer promotes invasion and migration of cancer cells through an interaction with α8 integrin." (PMID 28733469, 2017). "The upregulation of p21 by BMP-2 prevents EGF-induced proliferation of MDA-MB-231 breast cancer cells." (PMID 28733469, 2017). "TGF-β and BMP-2 signalling in murine mammary cancer cell lines results in transcription of genes that suppress the epithelial phenotype." (PMID 28733469, 2017). "This showed that native BMP-2 protein was produced in MCF-7 breast cancer cells at relatively low levels." (PMID 28725489, 2017). "BMPs and their antagonists can also influence the bone microenvironment, for example, orthotropic implant of silk scaffolds carrying BMP-2 showed increased metastatic spread of breast cancer cells to bone in vivo." (PMID 28733469, 2017). "In support of this conclusion, our immunohistochemical assays performed in clinical breast cancer samples also shown an inverse correlation between the expression levels of BMP-2 and Rb and a positive correlation between BMP-2 and CD44." (PMID 28725489, 2017). "A BMP2/7 heterodimer strongly reduced the size of a breast cancer stem cell population in vitro, and in vivo was able to inhibit formation of bone metastases." (PMID 28733469, 2017). "We also found that BMP-2 downregulated Rb protein through a Smad-independent PI3K/AKT signaling pathway in breast cancer cells." (PMID 28725489, 2017). "BMP2 has been reported to be highly expressed in breast cancer tissues and is related to breast cancer bone metastasis." (PMID 27806311, 2016). "BMP2 has been reported to be expressed in breast cancer cell lines and primary breast cancer tissues, and it is particularly elevated in breast cancer bone metastatic samples relative to metastases in other organs." (PMID 27806311, 2016). "Mechanistically, we demonstrated that the ectopic co-expression of BRGs in breast cancer cells is derived from EMT that has undergone BMP2 induction." (PMID 27806311, 2016). "Epigenetic silencing of BMP2 in breast cancer has also been found to promote breast cancer progression and drug resistance, as well defining a novel prognostic marker and offering novel therapeutic opportunities." (PMID 26664652, 2015). "Here we report that AB215, a chimeric ligand assembled from sections of Activin A and BMP2 with BMP2-like signaling, possesses stronger anti-proliferative effects on ERα positive breast cancer cells than BMP2." (PMID 25070479, 2014). "In vitro luciferase and MTT proliferation assays together with western blot, RT_PCR, and mRNA knockdown methods were used to determine the mechanism of inhibition of estrogen positive breast cancer cells growth by BMP2 and AB215." (PMID 25070479, 2014). "In the present study, we established that AB215 indeed inhibits E2-induced proliferation of ERα+ breast cancer cells to a greater extent than BMP2." (PMID 25070479, 2014). "We show that AB215 has stronger anti-estrogenic and anti-proliferative effects on breast cancer cells than BMP2." (PMID 25070479, 2014).
breast cancer (continued). "BMP2 is also reported to suppress the proliferation of MCF7 breast cancer cells by regulating the retinoblastoma and the phosphatase and tensin homolog proteins." (PMID 25070479, 2014). "MiR-379, in turn, downregulated the expression of BMP2 and a TGF-β target gene SERPINE1, both of which have been implicated in the development of breast cancer bone metastases." (PMID 22629385, 2012). "BMP2 is also known to be expressed in human breast cancers and injection of recombinant BMP2 into growing rodent mammary tumors results in mammary microcalcifications." (PMID 22911843, 2012). "BMP2 has also been shown to enhance the migration of MCF7 breast cancer cell line and its over-expression promotes tumor formation in a breast cancer xenograft model." (PMID 22729646, 2012). "On the other hand, treatment with BMP-2 in the breast cancer cell line C2C12 resulted in increased expression of Id-1, while BMP-2 also positively regulated the expression of Id-1 in certain cell contexts." (PMID 20010941, 2010). "In an in vivo breast cancer to bone metastasis model, the presence of BMP-2 in a scaffold increased the metastatic frequency of the breast cancer cell line SUM1315." (PMID 20010941, 2010). "While our bioinformatics analysis demonstrated that BMP2 transcriptional alterations correlated significantly with tumor metastasis, immune cell infiltration, and poor survival in patients with breast cancer, there still exists a substantial gap between genetic findings and experimental validation." (PMID 40936753, 2025). "Finally, we examined the effect of BMP2 expression on the survival rate of patients with breast cancer." (PMID 40936753, 2025). "In The Cancer Genome Atlas (TCGA) and the Molecular Taxonomy of Breast Cancer International Consortium (METABRIC) databases, the frequencies of BMP2 mutations were 1.2% and 2.1%, respectively, with amplification and deep deletion being the main types of gene alterations." (PMID 40936753, 2025). "Furthermore, we evaluated the expression by immunohistochemistry in patients with breast MCA and predicted the potential molecular functions of BMP2 in breast cancer through in silico analyses." (PMID 40936753, 2025). "Human breast cancer cell lines were stimulated with BMP2 and/or BMP6 to examine whether reversing the reduced BMP ligand expression could have an impact on β-CATENIN levels." (PMID 38731813, 2024). "High levels of BMP2 have been found in the tumor microenvironment of breast cancers and may promote epithelial transformation." (PMID 37762032, 2023). "In summary, the results from this study support the proposed hypothesis that TAMs could secrete BMP-2 to induce microcalcifications in breast cancer and may influence prognosis via multiple pathways including BMP-2 and its downstream factors." (PMID 34983451, 2022). "BMP-2 overexpression has been shown to be associated with microcalcifications and is found to be produced by the tumor microenvironment, but not by the breast cancer cells themselves." (PMID 34983451, 2022). "Therefore, in this study, we quantified the TAMs levels in breast cancer tissue and determined its correlation with the expression of BMP-2 and microcalcifications by immunohistochemical evaluation." (PMID 34983451, 2022). "Although TGF-β-induced EMT may render breast cancer cells with stem cell properties, BMPs, particularly heterodimeric BMP-2/7, antagonize TGF-β-induced EMT and reduce the aldehyde dehydrogenase (ALDH)h CD44h CD24l− CSC population." (PMID 35693928, 2022). "In contrast, BMP2 is known to promote bone metastasis by EMT in breast cancer." (PMID 34064589, 2021). "BMP2 could induce the proliferation of human breast cancer cells through interacting with type II BMP receptor." (PMID 32195173, 2020). "Several studies reported that BMP2 was a pro-oncogenic protein and could promote the progression of breast cancer, lung cancer, prostate cancer, etc., but others also demonstrated that BMP2 inhibited cancer proliferation." (PMID 32195173, 2020).
breast cancer (continued). "Thus, it is possible that in breast cancer, BMPs, and in particular BMP-2, can be involved simultaneously in EMT, BOLCs origin, and the formation of microcalcifications." (PMID 32498363, 2020). "Several other studies came to opposite conclusions that demonstrated that BMP2 could inhibit the proliferation of various cancer cell lines such as MDA-MB-231 breast cancer cells, osteosarcoma cells, and gastric cancer cells." (PMID 32195173, 2020). "To investigate the role of BMP-2 in the development of breast cancer stem cells (BCSCs), and to further elucidate the mechanisms underlying its influence on breast cancer metastasis, we conducted a comprehensive molecular study using breast cancer cell lines and clinical samples." (PMID 28725489, 2017). "In summary, our data demonstrated that the osteomimetic feature of breast cancer with ectopic co-expression of BRGs is obtained from the epithelial cancer cells that undergo stromal cell-induced EMT followed by BMP2-induced transcriptional activation function of RUNX2 in the tumor microenvironment." (PMID 27806311, 2016). "Promoter DNA methylation of BMP2 contributes to drug resistance in breast cancer." (PMID 26884818, 2016). "Another connection between OPN and Twist in breast cancer is through BMP-2." (PMID 27023622, 2016). "Interestingly, BMP2 while upregulated in basal breast cancers is more frequently downregulated in Luminal A and HER2 amplified subtypes." (PMID 26274893, 2015). "Moreover, a BMP2-responsive reporter assay in breast cancer cells displayed a 50% decrease in BMP2 signaling when treated with E2." (PMID 25070479, 2014). "However, in contrast to this anti-oncogenic effect, BMP2 has also been reported as a pro-oncogene in breast cancer by promoting cancer cell invasion, increasing hormone-independent cancer growth, and angiogenesis in vitro." (PMID 25070479, 2014). "Since BMP2 inhibits proliferation of ERα+ breast cancer cells, we hypothesized that the increased BMP2-like signaling activity of AB215 may augment AB215’s potency in anti-proliferation of ERα+ breast cancer cells." (PMID 25070479, 2014). "Although BMP2 can be made by breast cancer cells, BMP2 and BMP7 are growth-inhibitory for tumor cells and their bone metastases, suggesting that anabolic effects on bone may not be paramount in this context." (PMID 25757219, 2014). "Id genes are BMP2 target genes in osteoblastic cells and in the breast cancer cell line MCF-7." (PMID 24312319, 2013). "BMP2 has also been shown to decrease hypoxic cell death of breast cancer cells." (PMID 23593444, 2013). "However, BMP2 has been shown to inhibit proliferation in breast cancer cell lines that express SMAD1 and SMAD4." (PMID 22729646, 2012). "For example, studies have demonstrated that BMP-2 and its receptors are expressed in breast cancer, colon cancer, gastric cancer and that its expression may be associated with the biological behavior of the tumor." (PMID 20587070, 2010). "In addition several reports have shown a role of BMP-2 in invasion of lung, prostate, breast cancer cells and BMP-4 in ovarian cancer." (PMID 19366455, 2009). "Phosphorylated Smad-1/5, located in the nucleus, was detected in tumors derived from clones expressing high levels of BMPs, indicating an active BMP signaling pathway and BMP-2 stimulation of mammary tumor cell clones in vitro resulted in activation of the Smad-1/5 pathway." (PMID 19771160, 2009). "Recent evidence suggests that alterations in bone morphogenetic protein (BMP) signaling may influence breast cancer progression and metastasis; however, the specific function and regulatory targets of BMP2 in breast MCA pathogenesis are yet to be fully understood." (PMID 40936753, 2025). "Therefore, the loss of MXRA8 may influence intracellular signaling pathways that in turn alter the expression of genes like ADAMTS1, TIE1, and BMP2 that regulate breast cancer metastasis." (PMID 37762032, 2023).